LINC00841 (long independently transcribed non-coding RNA 841)
Gene: Long non-coding RNA gene on chromosome 10 (43,909,244 to 43,984,464, forward strand). Ensembl gene ENSG00000233395.
Diseases named in the same sentence as LINC00841 in open-access papers:
LINC00841 is named in the same sentence as 1 disease in open-access papers, as found by Europe PMC text mining. Sharing a sentence is not in itself a finding about the gene and the disease. The quoted sentences say what the papers report.
myocardial infarction (1 paper, 2018). Gross necrosis of the myocardium, as a result of interruption of the blood supply to the area, as in coronary thrombosis. "For instance, several studies have demonstrated the association of variants in the LINC00841 gene to myocardial infarction and CHD." (PMID 30567402, 2018). "This may suggest that the LINC00841 gene plays a role in conferring risk for CHD associated myocardial infarction across ethnic groups." (PMID 30567402, 2018).